CSH2 (chorionic somatomammotropin hormone 2)
Description:
Produced only during pregnancy and is involved in stimulating lactation, fetal growth and metabolism. Does not interact with GHR but only activates PRLR through zinc-induced dimerization.
Synonyms: PL; hCS-B; CSB; CS-2; GHB1
Tractability: Antibody: UniProt places it where antibodies can reach, with medium confidence; UniProt predicts a signal peptide or a membrane-spanning region; its Gene Ontology location is reachable by antibodies, with medium confidence.
Gene: Protein-coding gene on chromosome 17 (63,872,012 to 63,873,766, reverse strand). Ensembl gene ENSG00000213218.
Subcellular location: Secreted
Gene Ontology:
Molecular function: protein binding; growth factor activity; growth hormone receptor binding; hormone activity
Biological process: animal organ development; growth hormone receptor signaling pathway; positive regulation of receptor signaling pathway via JAK-STAT; response to nutrient levels
Cellular component: endoplasmic reticulum; vesicle; cytoplasm; endomembrane system; extracellular region
Genetic constraint (gnomAD): Loss-of-function variants: 9 observed, 14.36 expected, observed/expected ratio (o/e) 0.63, 90% interval 0.38 to 1.09. The synonymous counts are far from expectation, so gnomAD's model fits this gene poorly and the ratio says little. Missense variants: 152 observed, 198.99 expected, observed/expected ratio (o/e) 0.76, 90% interval 0.67 to 0.87. Synonymous variants: 61 observed, 85.59 expected, observed/expected ratio (o/e) 0.71, 90% interval 0.58 to 0.88.
Homologues: Orthologues: macaque CSH2 (80% identical), macaque GHV (79% identical), pig GH1 (63% identical), dog GH1 (62% identical), rabbit GHB1 (62% identical), mouse Gh (60% identical), rat Gh1 (60% identical), guinea pig Gh1 (59% identical), tropical clawed frog gh1 (47% identical), tropical clawed frog gh2 (40% identical), zebrafish gh1 (34% identical). Paralogues in human: CSH1 (99% identical), CSHL1 (93% identical), GH1 (85% identical), GH2 (80% identical), PRL (24% identical).
Diseases named in the same sentence as CSH2 in open-access papers:
CSH2 is named in the same sentence as 10 diseases in open-access papers, as found by Europe PMC text mining. Sharing a sentence is not in itself a finding about the gene and the disease. The quoted sentences say what the papers report.
breast carcinoma (1 paper, 2014). "The overall objective was to establish hPL, the product of the CSH1 and CSH2 genes, as a biomarker for breast cancer." (PMID 24475273, 2014).
gestational diabetes mellitus (1 paper, 2012). "We investigated how the mRNA expression profile of placental GH2, CSH1 and CSH2 genes and their alternative transcripts correlates with maternal pre-eclampsia (PE) and/or gestational diabetes mellitus (GD)." (PMID 22387044, 2012).
influenza (1 paper, 2010). An acute viral infection of the respiratory tract, occurring in isolated cases, in epidemics, or in pandemics; it is caused by serologically different strains of viruses (influenzaviruses) designated A, B, and C, has a 3-day incubation period, and usually lasts for 3 to 10 days. "As NS1 interacts with p85β via direct binding to SH3, iSH2, or cSH2 domain of p85β, it can be speculated that disturb this interaction by heterologously expressed SH3, iSH2, or cSH2 may be a potential anti-influenza strategy." (PMID 20653952, 2010).
osteosarcoma (1 paper, 2015). A usually aggressive malignant bone-forming mesenchymal neoplasm, predominantly affecting adolescents and young adults. "Next we examined the intracellular localization of these various GFP-SH2 proteins by expressing pGFP-SRC(SH2), pGFP-SHP1(NSH2), pGFP-SHP1(CSH2), pGFP-SHP2(NSH2) or pGFP-SHP2(CSH2) individually in human osteosarcoma U2OS cells, which were then plated on fibronectin-coated coverslips." (PMID 26681405, 2015).
SHORT syndrome (1 paper, 2017). A rare disorder characterized by multiple congenital anomalies, including short stature, hyperextensibility of joints, ocular depression, Rieger anomaly and teething delay in which the cause of the disease is a mutation in PIK3R1 gene. "Noticeably, most of the SHORT syndrome-linked mutations targeted a cSH2 residue or introduced a stop codon at the cSH2 domain, suggesting a dispensable role for the p85α cSH2 domain in the direct control of p110α activity." (PMID 28143957, 2017).
cancer (2 papers, 2011 to 2024). A tumor composed of atypical neoplastic, often pleomorphic cells that invade other tissues. "These were the most common causal mutation, R649W, which abolishes phosphotyrosine binding by the C-terminal SH2 (cSH2) domain, Y657X, which truncates the cSH2 domain, and E489K which, atypically, lies in the inter-SH2 domain where most cancer, overgrowth and APDS2-associated mutations lie." (PMID 38077044, 2024).
CSH2 also shares sentences with these, for which no sentence is quoted: tumor (3 papers); antibody deficiency (1); neuroendocrine tumors (1); pituitary tumor (1).